IFIT1 (interferon induced protein with tetratricopeptide repeats 1)
Diseases named in the same sentence as IFIT1 in open-access papers (continued):
Sharing a sentence is not in itself a finding about the gene and the disease.
cancer (53 papers, 2007 to 2026). A tumor composed of atypical neoplastic, often pleomorphic cells that invade other tissues. "Notably, HLA-I– cancer cells acquiring a mesenchymal status were associated with enhanced mRNA levels of the IFN-stimulated genes IFIT1, IFIT2, IFIT3, IFI6, IFI27, and CCL2." (PMID 35503263, 2022). "Besides, by promoting macrophage secreted phosphoprotein 1 (SPP1) expression and facilitating cancer-associated fibroblast and endothelial cell recruitment and activation through TANs, IFIT1 promotes a mesenchymal phenotype, which is associated with a poor prognosis." (PMID 38898490, 2024). "From a clinical standpoint, however, IFIT1 appears to represent a potential biomarker for prognosis, patient outcomes and treatment resistance in some cancer types." (PMID 40564154, 2025). "IFIT1 is frequently upregulated in DNA damage-resistant cancer cell sublines, including those resistant to radiation or chemotherapy and residual tumors following treatment, such as in estrogen receptor–negative breast cancer following chemotherapy." (PMID 40646573, 2025). "We observed a relatively significant correlation between IFIT1 expression and the level of immune infiltration of neutrophils, monocytes/macrophages, dendritic cells, and Treg cells in most cancers." (PMID 38898490, 2024). "IFIT1 affects cancer cell behavior through Wnt/β-Catenin signaling, and IFITM1, IFITM2, and IFITM3 are related to antiviral functions." (PMID 38424218, 2024). "Although more work is required to accurately elucidate the impact of IFIT proteins in cancer, recent investigations reveal that IFIT1, IFIT3, and IFIT5 promote metastasis, while IFIT2 acts against neoplastic cells by promoting apoptosis." (PMID 36851555, 2023). "Among epithelial cells, we identified the EP3 sub-cluster as cancer stem cells, based on high expression of IFIT1 and ISG15." (PMID 38328306, 2023). "Cancer stem cells with increased expression of IFIT1, IFIT2, IFIT3, and ISG15 were uniquely present in HGSOC and MMMT tumors." (PMID 38328306, 2023). "Among 33 types of human cancers, IFIT1, IFIT2, IFIT3, IFIT5 were abnormally expressed in 21, 23, 24 and 23 cancer types respectively." (PMID 37980495, 2023). "Amongst the upregulated genes were IFN stimulated genes (ISGs), including IFI44L and IFIT1, which were also induced in NK cells following reovirus treatment of cancer patients." (PMID 35156714, 2022). "Restricted cell cycle genes in interferon-inducible pathways include antiviral and anti-cancer activity (Ifit1 and Ifit2) and pro-inflammatory reactions recruiting immune cells to target cells (genes Stat1 and Unc5cl)." (PMID 34202278, 2021). "IFIT1 is an abundant product of interferon-stimulating genes that correlates with a poor prognosis in cancer." (PMID 33431054, 2021). "Given the relevance of type I interferon responses in cancer treatment, we wanted to evaluate its association with the Mø2:CXCL10 and T-cell:IFIT1 cell state colocalization signal in our spatial data." (PMID 34650042, 2021). "Using IHC staining of human samples, we identified IFIT1 as a surrogate marker for STAT1-IDO1 expression in cancer cells of human CRC." (PMID 32444775, 2020). "We also found that exosomes from EBV+ and EBV− cell lines failed to stimulate expression of FOS, c-Myc, and IFNB1, although the exosomes induced significant expression of the ISG IFIT1 in HSC3 cancer cells." (PMID 30389917, 2018). "Among these proteins, we have identified many differentially abundant proteins identified as having a role in cancer (IFIT1, FASTKD2, PIP4K2B, ARID1B, SLC25A33: overexpressed in TR; CALD1, CPA3, B3GALT5, CD177, RIPK1: overexpressed in NR)." (PMID 29681787, 2018). "Induced ZNF395 expression led to the upregulation of genes known to play a role in cancer as well as a subset of interferon (IFN)-stimulated genes (ISG) involved in antiviral responses such as IFIT1/ISG56, IFI44 and IFI16." (PMID 24086395, 2013).
cancer (continued). "In other cancer types, IFIT1 expression correlates with favorable clinical outcomes." (PMID 40564154, 2025). "Since the correlation between IFIT1 and neutrophils is broad, we obtained ST data for pan-cancer." (PMID 38898490, 2024). "And as expected, the transcribed mRNA and translated protein levels of IFIT1 were positively correlated in 10 available cancers (linkedomicsKB), suggesting that IFIT1 expression may be primarily regulated by pre-transcriptional modifications." (PMID 38898490, 2024). "As a result, MUC1-C was also necessary for expression of (i) OAS1, which attenuates PAR synthesis during DNA repair and promotes the ability of cancer cells to survive replicative stress, and (ii) IFIT1-3, MX1 and BST2, among others, which confer DNA damage resistance." (PMID 35681561, 2022). "We have identified many differentially abundant proteins already identified as having a role in cancer, such as the earlier discussed proteins IFIT1, FASTKD2, PIP4K2B, ARID1B and SLC25A33 (more abundant in TR) or CALD1, CPA3, B3GALT5, CD177 and RIPK1 (more abundant in NR)." (PMID 29681787, 2018). "Since activation of Wnt signaling in cancer cells decreased both IFIT1 and IFIT2, co-repression of these genes may confer the pro-survival properties to the cancer cells by increasing resistance to apoptotic signals." (PMID 29245969, 2017). "We then plotted the expression profile of the top four upregulated ISGs (IFIT2, ISG15, IFIT1 and IFIT3) among various cancer types from the TCGA database." (PMID 38926796, 2024). "Functional studies with IFIT proteins (IFIT1 and IFIT3) on various molecular signaling mechanisms implicates them in cancer progression and metastasis." (PMID 36766731, 2023). "EP3 showed a unique signature of interferon-stimulated genes IFIT1-3 (logFC >2.5), IFITM1-3 (logFC >0.6), and ISG15 (logFC = 2.5), previously characterized as markers of cancer stem cells (CSC)." (PMID 38328306, 2023). "IFIT1 is modulated by the JAK/STAT pathway and is an inflammation related protein that can be aberrantly expressed in cancer." (PMID 37047231, 2023). "Elevated levels of IFIT1, IFIT3 and IFIT5 have been shown to play significant roles in cancer progression, while the decreased expression of IFIT2 has been reported to enhance invasion, tumor progression, and drug resistance in various cancer types." (PMID 36979874, 2023). "We also found that MUC1-C is necessary for the expression of IFN-stimulated genes (ISGs), including IFIT1/3, OAS1/3, IFITM1, IFI44L and MX1, that promote DNA damage resistance, chronic inflammation and cancer progression." (PMID 34657147, 2022). "In particular, the expression levels of genes, such as IFI6, MX1, IFIT1, IFIT3, ISG15, OAS1, and OAS2, which belong to the cancer-promoting ISG subset IRDS, were markedly increased." (PMID 35618021, 2022). "From a functional point of view, genes involved in interferon signaling and cytotoxicity (IFIT1, IFIT3, and MX1) are upregulated in COVID/cancer cohort." (PMID 34716309, 2021). "Increased expression of IFIT1 and IFIT3 genes was observed in DNA damage-resistant sublines compared to parental cell lines in various cancers, including OSCC cells." (PMID 31921891, 2019). "Hypoxia-induced ZNF395 can transcriptionally up-regulate cancer-related genes and interferon-stimulated genes, such as IFIT1/ISG56, IFI44 and IFI16, in an IKK signaling-dependent manner." (PMID 27411336, 2016). "Considering the lack of IFIT1-related cancer research, we evaluated IFIT1 expression at the pan-cancer level." (PMID 38898490, 2024). "Although not as well characterized as IFIT1/2/3, IFIT5 has also been implicated in the progression of cancer, specifically bladder and prostate cancer." (PMID 36851555, 2023). "Interestingly, IFIT1 and IFIT3 genes are upregulated during cancer metastasis and invasion and mediate their growth-promoting actions by complexing and phosphorylating Hsp90 and its client proteins, including PKC, EGFR, Akt, and p38." (PMID 36766731, 2023).
cancer (continued). "In addition, the distribution of STAT1, STAT2, STAT3, STAT4, STAT5A, STAT5B, and STAT6 expression in CD8+ T cells in pan-cancer were displayed, which presented that STAT1 and STAT2 had prominent up-regulation in CD8+ T cell with ISG IFIT1." (PMID 36968603, 2023). "Indeed, the expression of CCL8, IFIT1, IFIT3, IFI27, MX1, and RSAD2 has previously been considered favorably prognostic in several types of cancer." (PMID 36180872, 2022). "Indeed, studies involving IFIT protein (IFIT1, IFIT3) functions and their participation in various molecular signaling mechanisms implicates them in cancer progression and metastasis." (PMID 36230929, 2022). "Transcriptional analyses of IL-6, RSAD2, IFIT1 and IFNB1 following treatment with the CPT analogue topotecan (Top) suggested that 15 and 21 out of 42 human cancer cell lines expressing STING showed increased IL-6 expression >2 fold after 6 and 24 h Top treatment, respectively." (PMID 35087822, 2021). "Indeed, the TLR3/dsRNA inhibitor complex, a competitive and high affinity inhibitor of dsRNA binding to TLR345, blocked the capacity of J1.1 cell exosomes to induce expression of IFIT1 and IFNB1 in HSC3 cancer cells (J1.1+inh)." (PMID 30389917, 2018). "HIV-infected J1.1 cell exosomes and synthetic HIV TAR RNA induced significant expression of TLR3-responsive ISGs IFIT1 and IFNB1 in SCC9 and HSC3 cells, suggesting that TAR RNA-bearing exosomes from HIV-1-infected T cells would signal through TLR3 in cancer cells." (PMID 30389917, 2018). "In this study, we discovered that IFIT1 and IFIT2 are negatively regulated by Wnt signaling in CRC cells and that suppressed expression of IFIT2 may confer pro-survival properties to cancer cells." (PMID 29245969, 2017). "In addition, IFIT1 and IFIT3 are critical for EGFR recycling and activation in other cancers." (PMID 35280763, 2022). "This concurrent induction of Il-6, Rsad2 and Ifit1 by CPT in TC-1 cells prompted us to broadly assess whether such convergent induction of the NF-κB and IRF3 branches was a frequent response to DNA damage in cancer cells." (PMID 35087822, 2021). "Additionally, the distribution of STAT1, STAT2, STAT3, STAT4, STAT5A, STAT5B, and STAT6 expression in CD4+ T cells in pan-cancer were also clearly illustrated, which showed that STAT1 and STAT2 expression were notably up-regulated in CD4+ Treg cell with marker OSA1 and CD4+ T cell with ISG IFIT1." (PMID 36968603, 2023).
bacterial infection (7 papers, 2016 to 2025). "As reported, IFIT1 regulated different stages of the host innate resistant response duration of both viral and bacterial infection and may modulate the inflammatory response in human astrocytes." (PMID 35941292, 2022). "Data showed that females exhibit higher levels of anti-viral type 1 interferons IFNA17, IFNA2, IFIT1, IFIT3 and IFNE in the immune tissues/cells, which serve as the first line of defense against viral and bacterial infections." (PMID 33271804, 2020). "To assess whether glial cell production of IFN-β during bacterial infection promotes ISG protein production, we measured the levels of two canonical ISGs, including IFN-induced proteins with tetratricopeptide repeats 1 (IFIT-1) and IFIT-3." (PMID 41341589, 2025). "In addition, a further 12 ISGs of 380 tested ISGs including STAT1, STAT2, JAK1, IRF9, IRF2, IRF7 are key elements of IFN signaling, and classical and well-known ISGs such as ISG15, PKR, MX1, IFIT1, PML, IFI27 play key roles in viral or bacterial infections." (PMID 30717477, 2019).
cardiovascular disease (3 papers, 2021 to 2024). "Moreover, there were also study reported that platelet derived levels of CRP and IL-6 were associated with IFIT1 which may involve in cardiovascular disease risk factors." (PMID 38321374, 2024). "Previous studies have demonstrated that IFIT1, IFIT3 and IFIT5 play an important regulatory role in cardiovascular disease." (PMID 34753383, 2021).
inflammatory myopathies (1 paper, 2023). "Using microarrays, IFIG expression levels (including ISG5, Mx1, OAS1, IFIT4, IFIT1, IFI44, OAS3, OAS2, IRF7, and IFI27) in muscle samples were higher in DM than in other inflammatory myopathies, such as inclusion body myositis, polymyositis, necrotizing myopathy, and myopathies with inflammation." (PMID 36979843, 2023). "In addition, the IFN6 score (ISG15, LY6E, IFI44, IFI27, IFIT1, and OAS1) was higher in 13 DM patients than in 40 patients with inflammatory myopathies (no patients had SLE or MCTD)." (PMID 36979843, 2023).
IFIT1 also shares sentences with these, for which no sentence is quoted: rheumatoid arthritis (3 papers); tuberculosis (3); asthma (2); dengue disease (2); H1N1 virus infection (2); immune disorders (2); latent infection (2); lung adenocarcinoma (2); measles (2); metastatic melanoma (2); myeloma (2); renal cell carcinoma (2); viral diseases (2); acute promyelocytic leukemia (1); Adrenocortical carcinoma (1); Ageusia (1); Alzheimer disease (1); Anosmia (1); antiphospholipid syndrome (1); Arthritis (1); Ataxia (1); Autoimmunity (1); bacterial sepsis (1); Bunyavirus infection (1); chlamydial infection (1); cholangiocarcinoma (1); chronic hepatitis C (1); colon adenocarcinoma (1); colorectal adenocarcinoma (1); colorectal tumor (1).
A further 37 diseases each share a sentence with IFIT1 in 1 paper.